OR4F16 (olfactory receptor family 4 subfamily F member 16)
Description:
Odorant receptor.
Synonyms: OR1-1; OR7-21
Gene: Protein-coding gene on chromosome 1 (685,716 to 686,654, reverse strand). Ensembl gene ENSG00000284662.
Subcellular location: Cell membrane
Pathways (Reactome):
Sensory Perception: Expression and translocation of olfactory receptors
Gene Ontology:
Molecular function: protein binding; olfactory receptor activity; G protein-coupled receptor activity
Biological process: detection of chemical stimulus involved in sensory perception of smell; G protein-coupled receptor signaling pathway
Cellular component: plasma membrane; membrane
Homologues: Orthologues: rat Or4f7 (83% identical), rat Or4f7c (82% identical), mouse Or4f7 (82% identical). Paralogues in human: OR4F29 (100% identical), OR4F3 (100% identical), OR4F21 (99% identical), OR4F15 (71% identical), OR4F6 (67% identical), OR4F4 (57% identical), OR4F5 (57% identical), OR4F17 (56% identical), OR4K5 (53% identical), OR4K17 (53% identical), OR4K15 (51% identical), OR4K1 (51% identical), and 116 more.